RAB11B (RAB11B, member RAS oncogene family)
Description:
The small GTPases Rab are key regulators of intracellular membrane trafficking, from the formation of transport vesicles to their fusion with membranes. Rabs cycle between an inactive GDP-bound form and an active GTP-bound form that is able to recruit to membranes different set of downstream effectors directly responsible for vesicle formation, movement, tethering and fusion. RAB11B plays a role in endocytic recycling, regulating apical recycling of several transmembrane proteins including cystic fibrosis transmembrane conductance regulator/CFTR, epithelial sodium channel/ENaC, potassium voltage-gated channel, and voltage-dependent L-type calcium channel. May also regulate constitutive and regulated secretion, like insulin granule exocytosis. Required for melanosome transport and release from melanocytes. Also regulates V-ATPase intracellular transport in response to extracellular acidosis. Promotes Rabin8/RAB3IP preciliary vesicular trafficking to mother centriole by forming a ciliary targeting complex containing Rab11, ASAP1, Rabin8/RAB3IP, RAB11FIP3 and ARF4, thereby regulating ciliogenesis initiation. On the contrary, upon LPAR1 receptor signaling pathway activation, interaction with phosphorylated WDR44 prevents Rab11-RAB3IP-RAB11FIP3 complex formation and cilia growth. Also interacts with RABL3 to promote ciliary vesicle formation.
Synonyms: H-YPT3; NDAGSCW
Tractability: Small molecule: a structure with a bound ligand is known. PROTAC: ubiquitination databases record sites on it; its protein half-life has been measured.
Gene: Protein-coding gene on chromosome 19 (8,389,981 to 8,405,873, forward strand). Ensembl gene ENSG00000185236.
Subcellular location: Recycling endosome membrane; Cytoplasmic vesicle, secretory vesicle, synaptic vesicle membrane; Cytoplasmic vesicle, phagosome membrane; Cytoplasmic vesicle
Subcellular location (Human Protein Atlas): Centriolar satellite; Vesicles; Basal body; Cytosol; Primary cilium
Pathways (Reactome):
Metabolism of proteins: RAB geranylgeranylation
Vesicle-mediated transport: TBC/RABGAPs
Gene Ontology:
Molecular function: cadherin binding; G protein activity; GDP binding; GTP binding; GTPase activity; myosin V binding; protein binding
Biological process: amyloid-beta clearance by transcytosis; cellular response to acidic pH; constitutive secretory pathway; endocytic recycling; establishment of protein localization to membrane; regulation of cilium assembly; regulation of monoatomic anion transport; regulation of protein localization to cell surface; insulin secretion involved in cellular response to glucose stimulus; melanosome transport; receptor recycling; regulated exocytosis; regulation of endocytic recycling; transferrin transport; vesicle-mediated transport to the plasma membrane
Cellular component: cytoplasmic vesicle; extracellular exosome; phagocytic vesicle; cytosol; Golgi apparatus; recycling endosome; recycling endosome membrane; synaptic vesicle; cytoplasm; phagocytic vesicle membrane; synaptic vesicle membrane
Genetic constraint (gnomAD): Loss-of-function variants: 7 observed, 20.01 expected, observed/expected ratio (o/e) 0.35, 90% interval 0.2 to 0.66. The upper end of that interval is the gene's LOEUF score, 0.66, which puts it in group 2 of 6, group 1 being the genes least tolerant of losing a copy. Missense variants: 189 observed, 308.35 expected, observed/expected ratio (o/e) 0.61, 90% interval 0.54 to 0.69. Synonymous variants: 138 observed, 128.36 expected, observed/expected ratio (o/e) 1.08, 90% interval 0.94 to 1.24.
Homologues: Orthologues: macaque RAB11B (100% identical), guinea pig RAB11B (99% identical), mouse Rab11b (99% identical), zebrafish rab11ba (96% identical), tropical clawed frog rab11b.2 (95% identical), Caenorhabditis elegans rab-11.1 (79% identical), rabbit RAB11B (75% identical). Paralogues in human: RAB11A (90% identical), RAB25 (58% identical), RAB2B (47% identical), RAB2A (46% identical), RAB14 (45% identical), RAB4B (44% identical), RAB1B (44% identical), RAB4A (44% identical), RAB43 (43% identical), RAB1A (43% identical), RAB8B (43% identical), RAB8A (41% identical), and 56 more.